DVL2 (dishevelled segment polarity protein 2)
Diseases named in the same sentence as DVL2 in open-access papers (continued):
Sharing a sentence is not in itself a finding about the gene and the disease.
pancreatic cancer (9 papers, 2015 to 2025). "First, the analysis of GEO databases (GSE15471, GSE16515) and IHC staining results of PDAC patients' tissue indicated that the level of DVL2 was elevated in pancreatic cancer (GSE15471, p < 0.0001, GSE16515, p = 0.0205)." (PMID 37859814, 2023). "In pancreatic cancer, the DVL2/β-catenin pathway was confirmed to facilitate progression mediated by KLF1229." (PMID 37859814, 2023). "Dvl-2 is a signaling molecule that functions in the Wnt signaling pathway highly expresses in pancreatic cancer cells." (PMID 37529006, 2022). "In a model of pancreatic cancer, Afadin regulates Snail expression by antagonizing the interaction between Dvl2 and FOXE1." (PMID 30473688, 2018). "In addition, DVL2/WNT/β-catenin axis has been identified as a driver of progression mediated by KLF12 in pancreatic cancer." (PMID 41135528, 2025). "KLF12 expression correlates with DVL2 and canonical Wnt pathway in clinical pancreatic cancer." (PMID 30866999, 2019). "Taken together, our findings further supported the notion that elevated KLF12 expression activates canonical Wnt pathway through transcriptional regulating Dvl2, which subsequently prevents β-catenin degradation and promotes β-catenin translocated to the nucleus in pancreatic cancer." (PMID 30866999, 2019).
glioma (8 papers, 2014 to 2025). A benign or malignant brain and spinal cord tumor that arises from glial cells (astrocytes, oligodendrocytes, ependymal cells). "For example, PLAGL2 (Pleomorphic adenomas gene-like 2) and Dishevelled-2 (DVL2) have been shown to activate Wnt pathway in glioblastomas and to sustain self-renewal in glioma CSCs independently of beta-catenin mutations." (PMID 28472177, 2017). "Research manifested that DVL2 takes part in the regulation of chemoresistance of gliomas via Wnt/β-catenin signaling." (PMID 37859814, 2023). "Peng at al reported that in addition to being upregulated in high-grade gliomas, CTHRC1 expression correlated with genes associated with the Wnt Signaling pathway (DVL3, DVL1, DVL2, ROR2, WNT3A, FZD6 and FZD5)." (PMID 36190948, 2022). "Dvl2 promotes self-renewal and tumorigenesis in human gliomas via activation of Wnt/β-catenin signaling." (PMID 26892600, 2016). "Combined collective public datasets from eight studies that are examining low‐grade gliomas and glioblastomas encompassing 4216 samples demonstrate the following distribution: somatic mutations were found in 8/4216 (0.19%) cases for DVL1, 12/4216 (0.28%) for DVL2 and 5/4216 (0.12%) for DVL3." (PMID 30468298, 2019).
gastric cancer (7 papers, 2016 to 2024). A primary or metastatic malignant neoplasm involving the stomach. "The depletion of endogenous DVL2 inhibited the proliferation, migration, and invasion of gastric cancer cells." (PMID 39594618, 2024). "The overexpression of DVL2 promotes gastric cancer initiation and progression mainly through aberrant activation of the Wnt/β-catenin signaling pathway." (PMID 39594618, 2024). "Using cell lines and 209 gastric cancer specimens, they investigated the role of DVL2 in gastric cancer." (PMID 39594618, 2024). "circ_0091741 blocks the binding of miR-330-3p to TRIM14, increases TRIM14 expression, further activates the Wnt/β-catenin signaling pathway by stabilizing Dvl2, enhances gastric cancer cell autophagy and antioxidant capacity." (PMID 39703839, 2024). "DVL2 overexpression plays a crucial role in the occurrence and development of gastric cancer." (PMID 39594618, 2024). "Therefore, DVL2 may become a new therapeutic target for gastric cancer." (PMID 39594618, 2024). "Epigenome-wide DNA methylation arrays have also identified the role of DVL2 and ETS1 methylation in diffuse- and mixed-types of early gastric cancers." (PMID 28418867, 2017). "While the mechanism by which CCNG2 inhibits LPR6 and DVL2 in EOC is not known, a recent report in gastric cancer indicated that CCNG2 downregulated DVL2 through the interaction with Dapper1 (DACT1), a Wnt signalling antagonist that has been shown to promote DVL2 degradation." (PMID 31829231, 2019).
colon cancer (6 papers, 2015 to 2025). "The decreases in the TCF promoter activity and invasion capability were lower following DDX3 knockdown than following CK1ε and Dvl2 silencing in colon cancer cells." (PMID 26892600, 2016). "There are also studies showing that DVL2 is involved in the progression of colon cancer." (PMID 30468298, 2019). "You et al46 reported that DVL2 was expressed in sporadic colon cancer tissues." (PMID 30013305, 2018).
cardiac hypertrophy (5 papers, 2021 to 2025). "WWP1 promotes K27-linked ubiquitin multichain assembly on DVL2, exacerbating cardiac hypertrophy via the DVL2/CaMKII/HDAC4/MEF2C pathway." (PMID 39949609, 2024). "Additionally, WWP1 stabilizes disheveled segment polarity protein 2 (DVL2) through K27-linked polyubiquitination, a process critical for cardiac hypertrophy." (PMID 39949609, 2024). "WWP1 also promotes atypical K27-linked ubiquitin multichain assembly on DVL2 and exacerbates cardiac hypertrophy via the DVL2/CaMKII/HDAC4/MEF2C pathway." (PMID 38674024, 2024). "WWP1 promotes pressure overload-induced cardiac hypertrophy by inducing K27-mediated polyubiquitination of dishevelled segment polarity protein 2 (DVL2), thereby enhancing the DVL2/CaMKII/HDAC4/MEF2C signaling pathway." (PMID 38129384, 2023). "In particular, DVL2 acts as an activator in pressure overload-induced cardiac hypertrophy." (PMID 34733849, 2021). "Our previous research found that E3 ubiquitin ligase WWP1 can stabilize DVL2 by catalyzing K27-linked polyubiquitination, and DVL2 positively correlated with WWP1 hypertrophic heart and mediated the regulation of the CaMKII/HDAC4/MEF2C axis in cardiac hypertrophy by WWP1." (PMID 34733849, 2021).
lung cancer (5 papers, 2014 to 2022). A malignant neoplasm involving the lung. "A similar effect of DVL2 inhibition on increasing Cis-Pt sensitivity had been observed previously in lung cancer cells." (PMID 31671889, 2019). "In the present study, we observed that ART, DHA, and ARTS inhibited the expression level of Wnt5-a/b, down-regulated those of LRP6 and Dvl2, and subsequently reduced those of downstream genes mediated by β-catenin (i.e., nanog, sox2, oct3/4, and cyclin D1) in two lung cancer cell lines." (PMID 27119499, 2016). "It is similar with our previous report in human lung cancer, the activity of TCF/LEF was increased by co-transfecting DACT2 and Dvl2 with wild-type or mutant-type β-catenin." (PMID 25375359, 2014).
ovarian carcinoma (5 papers, 2017 to 2024). A malignant neoplasm originating from the surface ovarian epithelium. "We found that a low expression level of CDKN2B and WNT11 was associated with longer survival in ovarian cancer patients, while high expression levels of SMAD3, ZFYVE16, BMP6, LEFTY1, and DVL2 were significantly associated with poor survival." (PMID 38403634, 2024). "In ovarian cancer, cyclin G2 repressed the Wnt/β-catenin signaling pathway by downregulating key Wnt components, including DVL2." (PMID 36364346, 2022). "Niclosamide, an FDA-approved anthelmintic, suppresses ovarian cancer stem cell proliferation by blocking the Wnt/β-catenin signaling via DVL2 and LRP6 inhibition." (PMID 36185280, 2022). "To elucidate the mechanism by which DACT1 suppresses ovarian cancer cell growth, we assessed the levels of the key mediators of canonical Wnt signalling, such as Dvl2 and β-catenin, in 3AO-DACT1." (PMID 28839145, 2017). "Our results, in OV2008 ovarian cancer cells, indicate that 15k, at 2 and 4 μM, significantly decreased the levels of DVL3, DVL2 and c-Myc." (PMID 28824426, 2017).
craniorachischisis (4 papers, 2008 to 2018). Craniorachischisis is the most severe form of neural tube defect in which both the brain and spinal cord remain open to varying degrees. "In yet another type of digenic cause, high frequencies of craniorachischisis are found in mutants that are double heterozygotes for mutations at two PCP genes of different gene families (e.g., Vangl2;Celsr1, Vangl2;Dvl2, Vangl2;Scrib, or Celsr1;Scrib)." (PMID 30134561, 2018). "In the Dvl2+/−;Dvl3−/− mutants that displayed craniorachischisis, the phenotype was even more severe." (PMID 19008950, 2008). "Craniorachischisis was also observed in two Dvl2+/−;Dvl3−/− mutants." (PMID 19008950, 2008). "In one type of digenic example, mutants are homozygous at both of two homologous PCP genes with functional redundancy (e.g., Dvl1;Dvl2 or Fzd3;Fzd6) and nearly all embryos have craniorachischisis; homozygotes for any one of these genes do not." (PMID 30134561, 2018).
glioblastoma (4 papers, 2017 to 2022). The most malignant astrocytic tumor (WHO grade IV). "Furthermore, when DVL2 activity was decreased in the glioblastoma cells it prevented tumour development in the immunodeficiency mice." (PMID 30468298, 2019). "A study by Pulvirenti et al55 report on increased DVL2 expression in 70% of glioblastomas." (PMID 30468298, 2019). "The authors confirmed the role of DVL2 in human glioblastoma by DVL2 gene attenuation using RNAi." (PMID 30468298, 2019). "In glioblastoma, RNF41 mediates the ubiquitination of Dvl2, leading to enhanced migration and invasion in glioblastoma." (PMID 36446779, 2022). "Furthermore, deletions of DVL1 were found in seven glioblastomas and deletions of DVL2 in two glioblastomas, while deletions of DVL3 were not reported." (PMID 30468298, 2019). "In some cancer cells, the Wnt pathway component DVL2 maintains glioblastoma multiforme (GBM) cell proliferation through canonical and noncanonical Wnt signaling." (PMID 33650028, 2021).
hepatocellular carcinoma (4 papers, 2021 to 2025). A malignant tumor that arises from hepatocytes. "Similarly, in hepatocellular carcinoma (HCC), toosendanin (TSN), a novel agonist of WWOX, dose-dependently increases WWOX mRNA and protein expression and enhances its interaction with STAT3 and Dvl2, thereby inhibiting both the JAK2/STAT3 and Wnt/β-catenin signaling pathways." (PMID 41228229, 2025).
astrocytomas (3 papers, 2018 to 2023). "DVL2 may be participated in the early stages of astrocytomas." (PMID 36875704, 2023). "The plots demonstrated that for low‐grade astrocytomas, the low expression levels of DVL1 and DVL2 are correlated to better both overall and disease‐free survival." (PMID 30468298, 2019). "Key regulators of the Wnt signalling, DVL1, DVL2 and DVL3, in astrocytomas of different malignancy grades were investigated." (PMID 30468298, 2019). "In GBM and Astrocytoma °II/°III specimens, as well as in primary GBM cells, we found significantly increased expression levels of DVL2 and TGFB1." (PMID 30366472, 2018). "Notably, GBM exhibited higher levels of TGFB1 and DVL2 as compared to Astrocytoma °II/°III (TGFB1: induction 1.5-fold ± 0.36, p = n.s.; DVL2: induction 2.1-fold ± 0.3, p < 0.001; n = 10 for Astrocytoma °II/°III)." (PMID 30366472, 2018).
basal cell carcinoma (3 papers, 2012 to 2023). A carcinoma involving the basal cells. "Similarly, mmu-miR-329 (targeting Axin1 and Dvl2) is participating in basal cell carcinoma." (PMID 22245972, 2012).
Brachycephaly (3 papers, 2018 to 2021). An abnormality of skull shape characterized by a decreased anterior-posterior diameter. "In order to evaluate the molecular contribution to brachycephalic skull shape, the DVL2 mutant breeds were genotyped for the previously identified brachycephaly associated Line insertion affecting SMOC 2 splicing." (PMID 30521570, 2018). "Our results strongly indicate brachycephaly and elongated soft palate in dogs with the DVL2 deletion allele and suggest that additional risk for BOAS may be conferred by the variant." (PMID 33599851, 2021). "Given the apparent polygenic pathogenesis of brachycephaly in dog breeds, and the essentially fixed nature of the DVL2 mutant allele in the Bulldog and Boston breeds, assigning specific skull morphometric sequelae to the DVL2 mutation is challenging." (PMID 30521570, 2018). "The cranial dysmorphology seen in Robinow patients and the more extreme nature of the brachycephaly in the DVL mutant dog breeds is, however, highly suggestive of DVL2’s involvement in the brachycephalic phenotype." (PMID 30521570, 2018).
Robinow syndrome (3 papers, 2018 to 2024). Robinow syndrome (RS) is a rare genetic syndrome characterized by limb shortening and abnormalities of the head, face and external genitalia. "In addition to the bulldog DVL2 frameshift mutation, human mutations causing Robinow syndrome have been identified in WNT5A, ROR2, FZD2, DVL1, and DVL3, which are all major components of the WNT5A-ROR pathway." (PMID 30521570, 2018). "Even in highly inbred Dvl2 knockout mice, only 90% were reported to have vertebral anomalies, and hemivertebrae and associated scoliosis/kyphosis are seen variably in >75% and <25% of cases with recessive and dominant forms of Robinow syndrome respectively." (PMID 30521570, 2018). "Altogether, our study strengthens the role of DVL2 as one of the contributors to the “bulldog type” morphology and features on the spectrum of human Robinow syndrome." (PMID 33599851, 2021). "Of these, receptor tyrosine kinase-like orphan receptor 2 (ROR2) and nucleoredoxin (NXN) are linked to autosomal recessive Robinow syndrome, whereas dishevelled genes (DVL1, DVL2 and DVL3), WNT5A and Frizzled2 (FZD2) have autosomal dominant inheritance (autosomal dominant Robinow syndrome)." (PMID 38967226, 2024). "Altogether, the quantitative and qualitative morphological changes confirm that the DVL2 deletion results in a syndromic phenotype resembling Robinow syndrome in humans, supporting the previous hypothesis of the canine Robinow-like syndrome." (PMID 33599851, 2021). "Most of the genes implicated in the pathogenesis of Robinow syndrome function in the non-canonical c-Jun N-terminal kinase (JNK)/planar cell polarity (PCP) pathway except for FZD2, DVL1, DVL2 and DVL3, which also operate in the canonical/β-catenin-mediated WNT pathway." (PMID 38967226, 2024). "Still, the features on the spectrum of human Robinow syndrome are not influenced solely by DVL2 in dogs: as an example, the brachycephalic, short-limbed and vertebral phenotypes are more extreme in English Bulldogs, French Bulldogs and Boston Terriers due to selective breeding." (PMID 33599851, 2021).
breast tumor (2 papers, 2016 to 2023). "We further showed that Dvl2 and activated β-catenin were inhibited by DACT2 re-expression in breast tumor cells." (PMID 27708215, 2016).
cervical cancer (2 papers, 2013 to 2022). A primary or metastatic malignant neoplasm involving the cervix. "In the present study, our results showed that DYNLT3 could inhibit Dvl2 expression in the Wnt pathway in cervical cancer." (PMID 35965516, 2022). "The Wnt signaling pathway, which consists of multiple factors (β-catenin, Dvl2, LRP6, Wnt, Naked, C-Myc and Axin1, etc.)involved in cell proliferation, differentiation, migration, and polarity, is associated with many cancers, including cervical cancer." (PMID 35965516, 2022). "Herein, we observed that DVL3, but neither DVL1 nor DVL2, was significantly up-regulated and associated with augmented Wnt/β-catenin signaling activity and cervical cancer cell growth." (PMID 23301094, 2013).
diabetes (2 papers, 2022 to 2023). "tRF‐1020 mimic suppresses endothelial angiogenic functions and alleviates diabetes‐induced retinal vascular complications by targeting DVL‐2‐mediated Wnt signalling." (PMID 36128646, 2022). "Furthermore, our study introduces the finding that in human AT, DVL2 expression is influenced by both fat depot, diabetes, sex, and obesity, aligning with previous research linking this gene to insulin sensitivity." (PMID 38139277, 2023).
intestinal tumor (2 papers, 2016). "Deletion of Dvl2 reduced the number of intestinal tumors formed in the APCMin mouse model." (PMID 26892600, 2016).
liver cancer (2 papers, 2021 to 2024). An epithelial or non-epithelial malignant neoplasm that arises from the liver. "Altogether, the results suggest that ASPM exerts its tumor‐promoting function through activating the Wnt/Dvl2/β‐catenin pathway in liver cancer." (PMID 34428354, 2021).
lung adenocarcinoma (2 papers, 2018 to 2023). A carcinoma that arises from the lung and is characterized by the presence of malignant glandular epithelial cells. "The expression level of DVL2 was reported significantly higher in lung adenocarcinomas than in squamous carcinomas, and was associated with poor tumor differentiation." (PMID 30591011, 2018).
Obesity (2 papers, 2023 to 2025). Accumulation of substantial excess body fat. "Taken together, these findings indicated that in the presence of sex, obesity, and T2D, the expression levels of DVL2, ETS1, and IL1RAP are dependent on the type of AT depot." (PMID 38139277, 2023). "This enabled us to pinpoint 3 significant common target genes (ETS1, DVL2, and IL1RAP) exhibiting markedly distinct expression profiles in both VAT and SAT among patients with obesity and T2D." (PMID 38139277, 2023). "Additionally, the binding site prediction analysis further supported the direct regulation of miR-221-3p and miR-222-3p in the gene regulatory networks of ETS1, DVL2, and IL1RAP concerning obesity and T2D." (PMID 38139277, 2023). "Collectively, our data suggest that the miR-221-3p/222-3p cluster could potentially regulate AT functionality through the modulation of DVL2, ETS1, and IL1RAP during obesity and T2D." (PMID 38139277, 2023).
PEComas (2 papers, 2022 to 2024). "Recent studies have revealed the presence of TFE3 gene rearrangements in 23% of PEComas, which involve the formation of gene fusions such as SFPQ/PSF::TFE3 and DVL2::TFE3." (PMID 38291475, 2024). "After their discovery in papillary renal cell carcinoma (PRCC) as PRCC-TFE3 gene fusion, further partnerships have been reported, including NONO, SFPQ, and DVL2 genes in papillary renal cell carcinomas and PEComas." (PMID 35225876, 2022).
prostate carcinoma (2 papers, 2017 to 2023). A carcinoma that arises from epithelial cells of the prostate gland. "DVL2 has been shown to enhance the metastatic potential of prostate cancer by upregulating expression of Wnt-3a, AR, and MMP." (PMID 37534375, 2023). "Moreover, recent work reported that Dvl2 was overexpressed in prostate cancer cell lines and tissues and its silencing by RNAi can reduce cell proliferation and migration." (PMID 28484252, 2017).
schizophrenia (2 papers, 2013 to 2024). A major psychotic disorder characterized by abnormalities in the perception or expression of reality. "Furthermore, we are unaware of any study linking DVL2 gene expression to psychosis or other major psychiatric disorders, although numerous studies have implicated GSK3B in the pathogenesis of schizophrenia as well as antipsychotic drug action." (PMID 24236287, 2013). "For instance, studies examining WNT signaling genes in the prefrontal cortex of patients with schizophrenia reported no changes in protein expression for β-Catenin, GSK3β, and DVL2." (PMID 39061390, 2024).
acute leukemia (1 paper, 2017). A clonal (malignant) hematopoietic disorder with an acute onset, affecting the bone marrow and the peripheral blood. "In our study, we found that p-BCR-ABL and classical Wnt/β-catenin signaling were significantly down-regulated (i.e., Dvl-2 and β-catenin were significantly down-regulated and p-GSK3β was significantly up-regulated) when CFTR protein was reduced by CFTRinh-172 and shRNA in Ph+ acute leukemia cells." (PMID 28445932, 2017).
acute myeloid leukemia (1 paper, 2025). Acute myeloid leukemia (AML) is a group of neoplasms arising from precursor cells committed to the myeloid cell-line differentiation. "Furthermore, NEAT1 translocated from the nucleus to the cytoplasm interacts with E3 ubiquitin ligase to promote DVL2 degradation, acting as a tumor suppressor in acute myeloid leukemia." (PMID 41268533, 2025).